RETSAT (retinol saturase)
Description:
Catalyzes the saturation of all-trans-retinol to all-trans-13,14-dihydroretinol. Does not exhibit any activity toward all-trans-retinoic acid, nor 9-cis, 11-cis or 13-cis-retinol isomers. May play a role in the metabolism of vitamin A. Independently of retinol conversion, may regulate liver metabolism upstream of MLXIPL/ChREBP. May play a role in adipocyte differentiation.
Synonyms: FLJ20296
Tractability: Antibody: UniProt places it where antibodies can reach, with medium confidence; UniProt predicts a signal peptide or a membrane-spanning region. PROTAC: ubiquitination databases record sites on it; its protein half-life has been measured.
Gene: Protein-coding gene on chromosome 2 (85,341,954 to 85,354,655, reverse strand). Ensembl gene ENSG00000042445.
Subcellular location: Endoplasmic reticulum membrane
Subcellular location (Human Protein Atlas): Cytosol
Pathways (Reactome):
Sensory Perception: Retinoid metabolism and transport
Gene Ontology:
Molecular function: all-trans-retinol 13,14-reductase activity
Biological process: retinol metabolic process; retinoid metabolic process
Cellular component: membrane; endoplasmic reticulum membrane; nuclear membrane; nuclear outer membrane
Genetic constraint (gnomAD): Loss-of-function variants: 35 observed, 64.33 expected, observed/expected ratio (o/e) 0.54, 90% interval 0.41 to 0.72. The upper end of that interval is the gene's LOEUF score, 0.72, which puts it in group 2 of 6, group 1 being the genes least tolerant of losing a copy. Missense variants: 670 observed, 784.42 expected, observed/expected ratio (o/e) 0.85, 90% interval 0.8 to 0.91. Synonymous variants: 277 observed, 324.13 expected, observed/expected ratio (o/e) 0.85, 90% interval 0.77 to 0.94.
Homologues: Orthologues: chimpanzee RETSAT (95% identical), macaque RETSAT (95% identical), rabbit RETSAT (85% identical), pig RETSAT (83% identical), guinea pig RETSAT (82% identical), dog RETSAT (81% identical), mouse Retsat (81% identical), rat Retsat (81% identical), tropical clawed frog retsat (49% identical), zebrafish retsat.2 (49% identical), zebrafish retsat.1 (47% identical). Paralogues in human: PYROXD2 (19% identical), BLOC1S2 (5% identical).
Diseases named in the same sentence as RETSAT in open-access papers:
RETSAT is named in the same sentence as 35 diseases in open-access papers, as found by Europe PMC text mining. Sharing a sentence is not in itself a finding about the gene and the disease. The quoted sentences say what the papers report.
Obesity (4 papers, 2014 to 2024). Accumulation of substantial excess body fat. "The downregulation of retinol saturase seen in this experiment is notable, as retinol saturase promotes adipogenesis and is downregulated in obesity." (PMID 28439422, 2017). "Finally, we tested whether diet-induced obesity upon feeding high-fat diet (HFD) regulates RetSat expression in iBAT." (PMID 38128827, 2024).
Autoimmunity (2 papers, 2019 to 2022). The occurrence of an immune reaction against the organism's own cells or tissues. "Loss of retinol saturase in mice leads to impaired efferocytosis, and to development of autoimmunity." (PMID 36139503, 2022). "Impaired efferocytosis in retinol saturase null mice resulted in the development of a mild autoimmunity." (PMID 36139503, 2022). "Like MFG-E8-null mice, aged female RetSat-null mice also develop SLE-like autoimmunity characterized by enlarged spleens, accumulation of apoptotic cells in the spleen, and anti-nuclear antibodies and immune complex deposits in the kidneys." (PMID 31766264, 2019). "If loss of RetSat impairs the in vivo clearance of apoptotic cells by macrophages, it is expected that RetSat-null female mice are also more prone to develop SLE-like autoimmunity." (PMID 31766264, 2019). "Thus, we cannot exclude that a possibly altered DC-STAMP expression in dendritic cells might also contribute to the development of autoimmunity in RetSat-null mice." (PMID 31766264, 2019).
fatty liver (2 papers, 2017 to 2020). "For retinol metabolism, the oxidoreductase retinol saturase gene (Retsat), which has been shown to correlate with the development of fatty liver disease, had a ∼4-fold increase in the male livers and an ∼8-fold increase in the female livers." (PMID 32188695, 2020). "Here we show that the oxidoreductase retinol saturase (RetSat) is involved in the development of fatty liver." (PMID 28855500, 2017).
steatosis (2 papers, 2017 to 2023). Increased lipid within the cytoplasm of cells. "In humans, hepatic RETSAT expression correlates with serum TGs and steatosis, and depletion of RETSAT in obese mice lowers hepatic and circulating TGs." (PMID 37755254, 2023). "Hepatic RetSat expression correlates with steatosis and serum triglycerides (TGs) in humans." (PMID 28855500, 2017).
Abdominal obesity (1 paper, 2021). Excessive fat around the stomach and abdomen. "Moreover, this study finds dietary quercetin could modulate MSG-induced gut microbiota dysbiosis, alleviate hypothalamic damage and down-regulate liver RetSat expression, thus ameliorating abdominal obesity." (PMID 33996881, 2021). "Furthermore, we disclosed that quercetin could improve gut microbiota dysbiosis, down-regulate RetSat expression in the liver, thus preventing MSG-induced abdominal obesity." (PMID 33996881, 2021).
Barrett esophagus (1 paper, 2022). Esophageal lesion lined with columnar metaplastic epithelium which is flat or villiform. "This suggests that RetSat in retinol metabolism pathway is emerging as a promising therapeutic target for ESCC, and atRA has a potential role in therapy and chemoprevention of patients with ESCC and Barrett’s esophagus." (PMID 35155234, 2022).
co-infection (1 paper, 2024). "A further protein showing elevated abundance in the co-infection groups, as compared to control fish was the all-trans-retinol 13,14-reductase, also known as retinol saturase." (PMID 38803570, 2024).
COVID-19 (1 paper, 2026). A disease caused by infection with severe acute respiratory syndrome coronavirus 2. "Gene-level association analysis revealed MTERF1, TUFT1 (encoding Tuftelin1), and RETSAT (encoding retinol saturase) as the most significantly associated genes, all enriched for LoFs in patients with COVID-19." (PMID 41500120, 2026). "Among the genes included in these pathways, we found NQO1, CAT, RETSAT, NDUFS3, and HSD3B7, which were all already found associated with COVID-19 severity from our gene-based burden test analysis." (PMID 41500120, 2026).
glioma (1 paper, 2021). A benign or malignant brain and spinal cord tumor that arises from glial cells (astrocytes, oligodendrocytes, ependymal cells). "However, higher expression of RETSAT was observed in gliomas, suggesting that RETSAT may have differential role in the central nervous system." (PMID 34805153, 2021).
Hypercalciuria (1 paper, 2025). "The Retinol Saturase (RETSAT) regulates mineral homeostasis, as evidenced by hypercalciuria and hypophosphaturia in RetSat-deficient mice." (PMID 40753194, 2025).
melanoma (1 paper, 2022). A malignant, usually aggressive tumor composed of atypical, neoplastic melanocytes. "We explored the effect of the most frequently mutated genes (RETSAT and SNRNP70) on the prognosis of the two ICI-treated cohorts (Allen-Melanoma and Miao-Melanoma)." (PMID 36059700, 2022).
pancreatic cancers (1 paper, 2022). "The expression of RETSAT was examined in TCGA (The Cancer Genome Atlas), human pancreatic cancer microarray, clinical specimens and cell lines." (PMID 36109793, 2022). "To study the roles of RETSAT in pancreatic cancers, we first downloaded the bulk transcriptional database from TCGA (The Cancer Genome Atlas)." (PMID 36109793, 2022).
pancreatic ductal carcinoma (1 paper, 2022). "Here we report that RETSAT gene plays key roles in TME hypoxia adaptation and gemcitabine chemotherapy in the context of pancreatic ductal carcinoma (PDAC)." (PMID 36109793, 2022).
Simpson-Golabi-Behmel syndrome (1 paper, 2024). Simpson-Golabi-Behmel syndrome is a rare X-linked multiple congenital anomalies syndrome, characterized by pre- and postnatal overgrowth, distinctive craniofacial features, variable congenital malformations, organomegaly and an increased tumor risk. "RetSat is upregulated during differentiation of murine 3T3-L1 and human Simpson-Golabi-Behmel syndrome-derived precursor cells, both adipocytes that show predominantly white characteristics." (PMID 38128827, 2024).
tumor (4 papers, 2020 to 2024). "Tumor cells can be protected from lipid peroxidation and cell death caused by different iron death inducers through the action of retinol saturase (RETSAT)." (PMID 38905394, 2024). "RETSAT mutation is correlated to occurrence of undifferentiated tongue sarcoma, and its expression is positively associated with tumor immune infiltration." (PMID 36109793, 2022). "In this study, we decided to verify the expression and mutation patterns of RETSAT in various human cancers, and compared the xneograft or chemical induced-tumor formation in RETSAT mutant and wild-type mice." (PMID 34805153, 2021). "Compared with normal pancreatic tissues (n = 252 cases), the RETSAT mRNA levels were dramatically high in tumor tissues (n = 174 cases) (P = 7.52 × 10− 15)." (PMID 36109793, 2022). "To verify the in vivo functional role of RETSAT during tumorigenesis, we performed both the xenograft tumor formation and DMBA/TPA induced cutaneous keratinocyte carcinoma formation assays." (PMID 34805153, 2021). "We firstly examined the mRNA expression patterns of RETSAT in different types of human cancers using the Tumor Immune Estimation Resource (TIMER) online database." (PMID 34805153, 2021). "Since at RA regulates differentiation, proliferation and apoptosis, inhibition of RETSAT is suggested a novel means to control neoplasms." (PMID 32264925, 2020). "Furthermore, we identify that the promoter region of RETSAT is highly methylated, which leads to its decreased expressions in tumor tissues comparing to normal tissues." (PMID 34805153, 2021). "We found that lower expressions of RETSAT transcripts correlate with higher tumor stages." (PMID 34805153, 2021). "Taken together, these data suggest that RETSAT functions as a tumor suppressor in SKCM." (PMID 34805153, 2021). "Consistently, we also verified the downregulation of RETSAT in tumor tissues in the GEO database." (PMID 34805153, 2021). "Regard to our findings that RETSAT might play as a tumor suppressor in most types human cancers, we hypothesized that the somatic mutations on RETSAT in SKCM tissues mostly cause loss-of-function." (PMID 34805153, 2021). "Therefore, to further explore the extrinsic and intrinsic mechanisms of RETSAT repressing tumor progression, the gene/protein interacting network as well as the expression profiles of the downstream bio-products, should be thoroughly characterized in the future." (PMID 34805153, 2021). "Since RETSAT might function as a tumor suppressor and immune infiltration was considered as a promising independent prognostic factor in cancers, we next used the TIMER database to investigate the correlation between RETSAT expression and immune infiltration." (PMID 34805153, 2021).
cancer (2 papers, 2021 to 2022). A tumor composed of atypical neoplastic, often pleomorphic cells that invade other tissues. "We show that higher expression of RETSAT is positively associated with immune infiltration in different human cancers." (PMID 34805153, 2021). "Therefore, we hypothesized that the highly methylation in RETSAT promoter DNA fragment might cause its decreased expressions in multiple types of human cancers, including SKCM." (PMID 34805153, 2021). "Here, we demonstrate that RETSAT is mostly downregulated in multiple types of human cancers, whose lower expression correlates with worse clinical outcome." (PMID 34805153, 2021). "However, whether or not RETSAT play any role in human cancers is still unknown." (PMID 34805153, 2021).
RETSAT also shares sentences with these, for which no sentence is quoted: Insulin resistance (2 papers); type 2 diabetes (2); Breast invasive carcinoma (1); cholangiocarcinoma (1); colon adenocarcinoma (1); dyslipidemia (1); erectile dysfunction (1); geographic atrophy (1); head and neck squamous cell carcinoma (1); Hyperglycemia (1); Kidney Chromophobe (1); lung adenocarcinoma (1); Lung squamous cell carcinoma (1); Pheochromocytoma and Paraganglioma (1); prostate adenocarcinoma (1); rectum adenocarcinoma (1); skin cutaneous melanoma (1); Thyroid carcinoma (1); viral infection (1).